ERG (ETS transcription factor ERG)
Diseases named in the same sentence as ERG in open-access papers (continued):
Sharing a sentence is not in itself a finding about the gene and the disease.
cancer (continued). "Conversely, ctDNA from both Patients 6 and 7 had mutations in two known cancer critical genes each (BRCA1 and IDH1, and ERG and KMT2C, respectively)." (PMID 35880692, 2023). "Its general expression is cancer unspecific, however in PCa a decrease in expression is linked to the TMPRSS2::ERG fusion." (PMID 37349736, 2023). "Exosomal miR-200b-3p from hepatocytes inhibited endothelial ERG expression, while reduction of miR-200b-3p in cancer cells promoted angiogenesis in HCC tissues by improving endothelial ERG expression." (PMID 37602326, 2023). "The TMPRSS2-ERG fusion is not only a cancer initiating event, but also required for the survival of ERG-expressing PC cells." (PMID 37973913, 2023). "Our findings implicate the role of ARPC1B in PCa invasion and metastasis in association with ERG and further support its prognostic value as a biomarker in association with ERG and PTEN in identifying aggressive phenotypes of PCa cancer." (PMID 35163398, 2022). "PDGFRA and PDGFRB have 0.49 and 0.53 of the correlation coefficiency for ERG expression, respectively, in S:E fusion-positive cancer." (PMID 36579559, 2022). "Loss-of-function mutations have been recently identified in factors that either target ERG for degradation or repress its functions, further highlighting the importance of the ERG pathway in this type of cancer." (PMID 35267426, 2022). "We previously studied the signaling pathways involved in T:E fusion-positive cancer using T:E fusion-positive cases selected based on ERG expression level." (PMID 36579559, 2022). "ERG overexpression in immortalized prostate epithelial and cancer cells increases the capacity of these cells to migrate and invade and controls the expression of genes involved in extracellular matrix remodeling, inflammation, migration and angiogenesis." (PMID 35267426, 2022). "The upregulation of the AKT signalling pathways has been observed to work in tandem with downstream ERG targets to make cancer progression more aggressive." (PMID 35563163, 2022). "The overexpression of ERG has also been observed in other cancer subtypes, such as leukemia and Ewing’s sarcoma, which indicate its potent potential as an oncogene." (PMID 35563163, 2022). "ERG has also been implicated in the epithelial–mesenchymal transition (EMT) in PCa cells, which increases the ability of cancer cells to metastasize." (PMID 35563163, 2022). "Here, we examined the immunohistochemical features of TZ and PZ cancers using three antibodies, ERG, PTEN, and SPINK1." (PMID 35475132, 2021). "Preliminary studies have shown that ERG and lncRNAs are involved in the progression of many cancers." (PMID 33898515, 2021). "When not considering race, the percentage of cases with any TMA spot or all TMA spots with cancer cells staining positive for GSTP1 was lower in those who were ERG+ than ERG-." (PMID 34191807, 2021). "Regarding the relationship between ERG/SPINK1 expression and clinicopathological parameters, among TZ cancers, ERG‐/SPINK + cases showed a significantly lower BCR‐free survival rate than ERG‐/SPINK1‐ cases." (PMID 35475132, 2021). "In the TZ cancer group, statistical analyses were conducted only between ERG‐/SPINK1‐ and ERG‐/SPINK1 + subgroups because of the extremely lower prevalence of ERG‐overexpression in this group." (PMID 35475132, 2021). "Although ERG gene was supported as a key factor by experimental data in other cancer types, more robust experimental validation is needed in CRC." (PMID 34917613, 2021). "The expression of 4.1N mRNA is lower in cancer tissues with elevated ERG mRNA expression than in cancer tissues with close to normal ERG expression; however, the difference is not statistically significant." (PMID 34589518, 2021).
cancer (continued). "Here, we show that SPOP- and ERG-mutant cancer subtypes are driven by antagonistic tumorigenic pathways involving fundamentally different roles of SPOP and androgen receptor signaling levels." (PMID 33531470, 2021). "Several studies have shown the lower prevalence of TMPRSS2/ERG gene fusion/ERG‐overexpression in TZ cancer cases." (PMID 35475132, 2021). "We provide some evidence (in two treatment-naïve cohorts) that BRD9 is overexpressed in ERG fusion positive cancers and that ERG expression is very weakly correlated with BRD9 expression." (PMID 34944438, 2021). "In terms of association with other molecular alterations, GSTP1 positivity was enriched in ERG positive cancers among Black men." (PMID 34191807, 2021). "BRD9 warrants further investigation in ERG fusion positive cancers and possibly co-targeted with ERG inhibition, as ERG depends on BAF complexes for its epithelial to mesenchymal transition (EMT)." (PMID 34944438, 2021). "The percentage of patients with ERG positive cancers that were also GSTP1 positive was 23.1% in Black men, but only 5.1% in White men, a difference that was statistically significant (P = 0.001)." (PMID 34191807, 2021). "In ERG‐positive cancers, the percentage of patients with strong AR expression was drastically increased despite low JUP levels." (PMID 33533127, 2021). "In recent years, the new antibody (e.g. ERG and Fli1) mainly expressed in the vascular endothelium can be used to mark benign and malignant tumors of vascular origin with high specificity." (PMID 33509230, 2021). "Alternatively, it cannot be excluded that our IHC protocol was not optimally suited to reveal hnRNPA1’s prognostic value specifically in the subset of ERG-positive cancers." (PMID 32417965, 2020). "There were 5142 ERG-negative and 4441 ERG-positive cancers by ERG-IHC analysis, as well as 3393 ERG-negative and 2803 ERG-positive cancers by ERG-FISH analysis." (PMID 32417965, 2020). "By mining public databases, a few scholars have studied the relationship between the EMT-related gene (ERG) signature and the prognosis of patients with cancer, such as glioma, gastric adenocarcinoma, and head and neck squamous cell carcinoma." (PMID 33343628, 2020). "SEs also mediate the overexpression of the v-ets erythroblastosis virus E26 oncogene homolog (ERG), resulting in target gene expression to promote cancer development." (PMID 32382065, 2020). "Cancer samples with ERG alterations assigned to signature LPD3 also exhibited better outcome (P < 0.05, log-rank test, comparison to all other ETS-positive cancer samples) in all three datasets where ERG status was available." (PMID 32203215, 2020). "These associations also hold true in the subset of ERG‐negative and ERG‐positive cancers (P < .0001 each)." (PMID 31893572, 2020). "Taken together, these results suggest that the use of ERG-targeting SSOs is a viable approach for reducing ERG protein expression in multiple cancer cell lines." (PMID 32581342, 2020). "High TFAP2D expression was strongly linked to TMPRSS2:ERG rearrangement and ERG expression: TFAP2D positivity increased from 66.5–73.5% in ERG negative cancers (by IHC or FISH) to 88.2–89.8% in ERG positive cancers (p < 0.0001 each)." (PMID 32143573, 2020). "In our study, both ESRP1 and ESRP2 were more frequently expressed in ERG-positive than in ERG-negative cancers." (PMID 33339518, 2020). "In ERG-positive cancers, a statistically significant difference was found for ESRP1 in 5 and for ESRP2 in 1 of the analyzed loci." (PMID 33339518, 2020). "A search for associations between hnRNPA1 and deletions must, therefore, be restricted to subgroups of ERG-positive and ERG-negative cancers." (PMID 32417965, 2020). "Multivariate analysis revealed the cytoplasmic CD138 expression as an independent prognostic parameter in all cancers and in the ERG positive subgroup." (PMID 33195694, 2020).
cancer (continued). "They concluded that cancer patients overall have an increased risk of SARS-CoV-2 infections than non-cancer patients, however, details on TMPRSS2:ERG patient status are missing." (PMID 33243086, 2020). "Out of these cancer-specific fusions, 38 were predicted to produce 2 or more unique proteins (with ERG-TMPRSS2 predicted to produce 4 different unique proteins)." (PMID 32843691, 2020). "The significant upregulation of PNUTS in cancers having a TMPRSS2:ERG fusion demonstrates that PNUTS is either directly or indirectly impacted by ERG expression." (PMID 32377272, 2020). "A concordant result of IHC and FISH determined ERG status was found in 5291 of 5535 (95.6%) cancers for which both data were available." (PMID 32143573, 2020). "Detectable TFAP2D expression was strongly linked to outcome in ERG negative cancers (p < 0.0001) but completely unrelated to patient outcome in ERG positive cancers (p = 0.9543)." (PMID 32143573, 2020). "Independent prognostic impact, although weaker, was also seen in the ERG positive cancer subset (p < 0.005 each)." (PMID 31606028, 2019). "The discovery of the TMPRSS2:ERG gene fusion shifts the current paradigm in cancer genomics from experimental to bioinformatics approaches." (PMID 31303963, 2019). "In ERG positive cancers only high Gleason grade (p< 0.0001) remained as significantly linked to ELAC2 expression." (PMID 31452838, 2019). "Among the cancer samples, 34 samples were classified as having high levels of ERG (ERGhigh), while 30 and 31 samples were classified as ERGlow and ERGintermediate, respectively." (PMID 30791464, 2019). "Earlier studies have shown that TGF-ß signaling is massively up regulated in ERG-positive cancers, and that TGF-ß1 increases SNW1 expression in mouse models." (PMID 31043167, 2019). "As ERG is largely involved in the biology of cancer, it can be considered as a potential new target for cancer therapies itself." (PMID 31817884, 2019). "The expression of ERG was significantly higher in cancer samples compared to benign samples (P < 0.001)." (PMID 31537872, 2019). "The ETS (E-26 transformation-specific) transcription factor (TF) ERG (ETS-related gene) is essential for endothelial homeostasis, whereas its aberrant overexpression in cancer is oncogenic." (PMID 30892142, 2019). "At odds with its homeostatic role in EC, aberrant ERG expression due to chromosomal translocations, such as the TMPRSS-2:ERG gene fusions in prostate cells, is a hallmark of cancer (reviewed in Adamo and Ladomery14)." (PMID 30892142, 2019). "It is well conceivable that differences in the cellular microenvironment with more than 1600 dysregulated genes in ERG activated cancers impact the biological effect of molecular features such as PTPN12." (PMID 31606028, 2019). "Several splice variants that are known to be involved in cancer have been identified in PCa, including VEGFA, KLF6, BCL2L2, ERG, FGFR2, TMPRSS2-ERG and AR 3,4." (PMID 31632503, 2019). "In ERG positive cancers, a statistically significant difference was still seen for 7 of 12 analyzed deletions (p < 0.05 each)." (PMID 31606028, 2019). "In summary, we have discovered that sGC is a novel transcriptional target of TMPRSS2-ERG in PCa cells, and showed that the sGC-mediated NO-cGMP pathway was a critical downstream effector of ERG in promoting cancer cell proliferation and tumorigenesis." (PMID 30718921, 2019). "Because of the strong link between BAP1 overexpression and ERG rearrangement, the analysis was repeated in the subsets of ERG-negative and ERG-positive cancers." (PMID 31903168, 2019). "A recent study reported that 1-[2-Thiazolylazo]-2-naphtol (called ERGi-USU) acts as an ERG inhibitor, inhibiting the growth of ERG-positive cancer cell lines." (PMID 31366128, 2019). "ERG’s homeostatic function is lineage-specific, because aberrant ERG expression in cancer is oncogenic." (PMID 30892142, 2019).
cancer (continued). "This increased propensity to coexpress p16 and ERG‐positive PCa in AA patients in part compensate for the lower fraction of ERG‐positive cancers to make the EA and AA PCa more equal in p16 expression." (PMID 31111520, 2019). "BAP1 expression was linked to ERG-fusion type cancers, with strong BAP1 staining in 12% of ERG-negative, but 30% of ERG-positive cancers (p<0.0001)." (PMID 31903168, 2019). "For example, the prognostic impact of SOX9, SENP1 and mTOR was limited to ERG positive cancers while FOXA1, MTCO2 and FOXP2 were only prognostic in ERG negative cancers." (PMID 31606028, 2019). "This diversity among ETS-positive subtypes is consistent with results from previous studies that suggest substantial molecular and clinicopathological differences between ERG- and non-ERG ETS-rearranged cancers." (PMID 29581876, 2018). "Data on both ERG FISH and ERG IHC were available from 5938 cancers, and an identical result (ERG IHC positive and rearrangement by FISH or ERG IHC negative and missing rearrangement by FISH) was found in 5666 of 5938 (95.4%) cancers." (PMID 29304771, 2018). "Of these primary cancers, 75% were classified into seven subtypes, defined by either specific gene fusions of ETS transcription family members (ERG, ETV1, ETV4, and FLI1) or mutations (SPOP, FOXA1, and IDH1)." (PMID 29581876, 2018). "For example, moderate or strong BCAR1 staining was observed in 79.3% of cancers with ERG rearrangement detected by FISH but found in only 57.3% of cancers without such rearrangements (p < 0.0001)." (PMID 29304771, 2018). "For example, in ERG-negative cancer, strong BCAR1 expression was found in 27.9% of pT2 cancers and increased by 9.3% to 37.2% in tumors ≥ pT3b, while the difference in ERG-positive cancer was only 1.7% between pT2 (51.9%) and ≥ pT3b (50.2%)." (PMID 29304771, 2018). "Data on both ERG FISH and immunohistochemistry (IHC) were available from 5978 cancers, and an identical result (ERG IHC-positive and break by FISH, or ERG IHC-negative and missing break by FISH) was found in 5712 of 5978 (95.6%) cancers." (PMID 28146062, 2017). "FAM13C expression was found in 85.4% of cancers with immunohistochemical ERG expression and in 87.6% of tumors with ERG rearrangement by FISH, but in only 53.6% (IHC) and 61% (FISH) ERG negative cancers (p < 0.0001 each)." (PMID 28415558, 2017). "Since GGH showed differential expression in ERG-positive and ERG-negative cancers, we also analyzed both subsets separately." (PMID 28146062, 2017). "Data on both ERG FISH and IHC were available from 6,778 cancers, and an identical result (ERG IHC positive and break by FISH) was found in 6,463 of 6,778 (95.4%) cancers." (PMID 28415558, 2017). "At least weak ERCC1 staining was found in 85.4% of cancers with immunohistochemically detected ERG expression and in 81.4% of tumors with ERG-rearrangement, but only in 52.6% (IHC) or 61.8% (FISH) of ERG-negative cancers (p < 0.0001 each)." (PMID 28747165, 2017). "The relationship with patient outcome was similar in the subsets of 3,231 ERG-negative (P < 0.0001) and 2,738 ERG-positive cancers (P < 0.0001)." (PMID 27880722, 2017). "In fact, the most common translocation known to cancers is TMPRSS2-ERG fusion, which introduces a strong regulating element from the androgen receptor gene upstream of the ERG gene." (PMID 28255369, 2017). "After TMPRSS2:ERG fusion, 8p deletions constitute the second most frequent genomic alteration in this tumor type, occurring in about 30% of cancers." (PMID 27880722, 2017). "In elderly patients, 3 % of cancers were homogeneously and 57 % were heterogeneously ERG positive (p = 0.0721)." (PMID 27530104, 2016). "Overexpression of PLA2G7 as a member of arachidonic acid and prostaglandin pathway in PCa, specifically in ERG positive cancers, has been reported." (PMID 27196083, 2016). "Since microRNA (miRNA) has crucial functions in cancer, we searched for miRNAs regulated by ERG in PCas." (PMID 27191272, 2016).
cancer (continued). "Depending on the sequel of development of MAP3K7 deletions and ERG-expression, one can expect a small area of cancer having both alterations within a larger area having only the first one of these changes." (PMID 26684029, 2016). "The very high rate of heterogeneity (89 %) found for “ERG positive” cancers highlights the importance of cancer heterogeneity." (PMID 27530104, 2016). "TMPRSS2:ERG expression was highest in the Bx Pos group (P = 0.013) consistent with the confirmed presence of cancer (see S4 Fig for box plot distribution of delta Ct)." (PMID 27144529, 2016). "The second involves the testing of biopsied tissue from the prostate gland to assess the expression of ERG oncoprotein by immunohistochemistry (IHC) for stratification of cancer status." (PMID 28191285, 2016). "The data from this study revealed a striking link of strong HOXB13 expression with PTEN deleted ERG positive cancers." (PMID 25825985, 2015). "Many novel MAPK targets and specificities were identified within the ETS family, including the identification of the prostate cancer oncoprotein ERG as a specific target of ERK2." (PMID 25885538, 2015). "Wnt signaling has been shown to be a critical mediator of ERG-induced oncogenesis in several types of cancer, where aberrant ERG overexpression is a marker of aggressive malignancy and associated with increased proliferation." (PMID 25584796, 2015). "A further subset analysis of ERG positive/PTEN undeleted cancers revealed independent prognostic impact, however, in 3 of 4 tested scenarios." (PMID 26202067, 2015). "While these roles suggest an important role for ERG in tumorigenesis, in vivo mouse models have found that ERG overexpression alone is insufficient to induce cancer." (PMID 26310325, 2015). "Studies have also shown that ERG overexpression increases cancer invasiveness and has been correlated to increased metastasis in the clinic." (PMID 26571387, 2015). "The tissue regions that were positively stained in ERG IHC matched the locations of carcinoma lesions, and either contained detectable TMPRSS2-ERG mRNA or were located adjacent to samples that did." (PMID 26294063, 2015). "Since Ki-67 is a known strong prognosticator in PCa and has independent predictive value for cancer-related survival in our cohort, we directly compared the prognostic effects of ERG rearrangement and Ki-67 LI in combination." (PMID 24516518, 2014). "MiR-196b-5p is dysregulated in many malignancies, has been related to cancer prognosis, and targets c-myc, ERG, MEIS1, FAS, ABL1, BCL-2 and several HOX genes." (PMID 25329796, 2014). "ERG-overexpressing cancer cells demonstrated higher single-strand break repair (SSBR) rate and leaded to radiation resistance." (PMID 24739220, 2014). "Our data provide new information on a subtype of cancer samples enriched for gene sets related to ERG-fusion, ESC and MYC + indicating poor prognosis on an early stage of PCa development (low Gleason score)." (PMID 25115192, 2014). "Apart from a pronounced migratory and dedifferentiated phenotype, ERG-related cancer-promoting functions remained largely undefined." (PMID 23390522, 2013). "The difference in oncoprotein expression was significantly more pronounced in higher grade cancers; 59% (10/17) of CA patients were ERG positive while only 10% (2/20) of AA men were ERG positive." (PMID 23892597, 2013). "Although we detected high levels of ERG mRNA in several cancer cell lines derived from the hematopoietic lineage, the corresponding expression of TDRD1 mRNA was approximately 50-fold lower than in VCaP cells." (PMID 23555854, 2013). "We previously reported a panel of TMPRSS2:ERG fusion-subtype markers for urine-based cancer detection with high specificity and sensitivity." (PMID 24133629, 2013).